RAD51 (RAD51 recombinase)
Diseases named in the same sentence as RAD51 in open-access papers (continued):
Sharing a sentence is not in itself a finding about the gene and the disease.
cancer (continued). "Gene knockouts display growth defects, reduced RAD51 focus formation, spontaneous chromosome abnormalities, sensitivity to PARP inhibitors and replication fork defects, but their precise molecular roles in fork stability, DNA repair and cancer avoidance remain unknown." (PMID 37344587, 2023). "However, so far, a systematic pan-cancer analysis of RAD51 has not been done yet." (PMID 35359409, 2022). "However, this is not true for spontaneously elevated (dysregulated) RAD51/HR in cancer situation." (PMID 36428789, 2022). "Moreover, the hypothesis implies that RAD51 missense mutations that abolish HR but retain the DNA-binding capacity of RAD51 should not promote cancer." (PMID 34316706, 2021). "Although BRCA1/2 is the most common genetic variant detected on germline testing, it is prudent to recognise non-BRCA HRR-related genes such as PALB2, ATM and RAD51 can also contribute to HBOC and other carcinomas." (PMID 39796639, 2024). "Cancer cell lines A375M, ILSA, Mel624, and pMelL showed a reduction of RAD51 foci after blocking the second DSB non-homologous end-joining repair pathway by treating cells with a DNA-PK inhibitor." (PMID 36229655, 2023). "Thus, gene alterations of RAD51 might not be the major reason that drives cancers." (PMID 35359409, 2022). "Although we have also observed the reduction of Rad51 and RPA foci, suppression of homologous recombination repair cannot explain the mechanism of neither cancer specific radiosensitization nor radiosensitization of G1 phase synchronized A549 cells." (PMID 29414878, 2018). "We found that in cancer cells, DNA damage is strongly induced by silencing SLD5 expression, as observed in MEFs; however, Rad51 rapidly increased and cell cycle restoration was not greatly affected." (PMID 25334017, 2014). "Since DNA repair mechanisms are of great interest in cancer research, it is not surprising that some of the most studied genes for cancer treatment, such as BRCA1 and RAD51, have an equally high number of reports showing miRNA-mediated regulation of these genes." (PMID 35328651, 2022). "However, CHD4 knockdown did not affect the expression of RAD51 or p21, the known targets of CHD4 in other cancer types that can modulate platinum sensitivity." (PMID 34161330, 2021). "Our results show that in the absence of DNA damage, the number of γH2AX foci or RAD51 foci is comparable in all cell lines including in cells depleted of BRCA2; this is probably due to the high genome instability intrinsic to these cancer cells." (PMID 32286328, 2020).
tumor (495 papers, 1999 to 2026). "Patients harbouring mutations in RAD51 paralogs appear to derive clinical benefit from PARPi therapy similar to that observed in BRCA/PALB2‐mutant tumours." (PMID 41537447, 2026). "Elevated RAD51 expression is significantly associated with advanced tumour stage, poorer clinical outcomes and reduced treatment response." (PMID 41350246, 2025). "The results revealed that RAD51 and its closely associated genes were significantly positively correlated with malignant phenotypes in tumours, including cell proliferation, cell cycle progression, DNA damage repair and invasion (p < 0.05)." (PMID 41350246, 2025). "Tumor cells deficient in BRCA1 or RAD51, or those with compromised DNA repair mechanisms, cannot effectively repair DNA damage and thus show heightened sensitivity to platinum-based chemotherapeutic agents." (PMID 41353219, 2025). "Stable isotope tracing (U-13C-glucose, n=3) demonstrated that RAD51 inhibition increased intratumoral lactate production by 2.1-fold, which in turn polarized tumor-associated macrophages (TAMs) toward an M2-like, pro-tumor phenotype (CD206+, p = 0.02)." (PMID 41487593, 2025). "Knocking down NEK8 was effective in reducing tumor proliferation but loss of NEK8 also reduced RAD51 localization, promoting HR deficiency." (PMID 39975112, 2025). "We showed that both sgRNA-1 and sgRNA-2 cells were characterized by a significantly reduced ability to load TOPBP1 and RAD51 and were more susceptible to cisplatin or talazoparib, as well as reduced tumor volume or weight." (PMID 38762174, 2024). "Of note, an exploratory analysis showed that patients with homologous recombination deficient (HRD) tumours, as determined by a RAD51 foci formation assay, had prolonged mPFS as compared to patients with proficient tumours (11.2 vs. 5.4 months)." (PMID 39796641, 2024). "The level of RAD51 expression has been shown to influence the risk of solid tumor development and, if a tumor is already present, to influence its sensitivity to anticancer therapy (and thus progression-free survival)." (PMID 36837562, 2023). "In conclusion, Rad51 has been observed to be dysregulated in various tumor types, and associated with unfavorable clinicopathological factors and prognosis." (PMID 35875146, 2022). "Assessment of the functionality of the DNA homologous recombination repair pathway by RAD51 foci in the tumor revealed a profile of homologous recombination deficiency." (PMID 36185283, 2022). "Our assumption that canonical HDR functions (RAD51 loading/filament stabilization) underlie BRCA2’s role in tumor suppression seems likely but requires definitive proof." (PMID 36098506, 2022). "RAD51 recruitment DNA breaks are a hallmark of HR pathways, that immunofluorescence can detect on formalin-fixed paraffin-embedded tumor samples." (PMID 35158866, 2022). "In total, 70 out of 74 (95%) diagnostic FFPE tumor specimens passed the QC and were successfully analyzed with the RAD51-FFPE test." (PMID 34203855, 2021). "The antibiotic Novobiocin was shown to inhibit Polθ, thus decreasing viability of HR-deficient tumor cells due to accumulation of toxic RAD51 foci." (PMID 34201502, 2021). "Quantification of yH2AX foci, a marker for DNA damage, confirmed that indeed most BC tumors contained sufficient endogenous DNA damage levels and RAD51 foci were detectable in diagnostic FFPE tumor specimens." (PMID 34203855, 2021). "The hyperactivation of RAD51 contributes to increased homologous recombination associated with tumor progression and metastasis." (PMID 34067336, 2021).
tumor (continued). "Cells deficient in RAD51-mediated HDR through the inactivation of tumor suppressor genes like BRCA1 or BRCA2 exhibit hypersensitivity to poly-ADP ribose polymerase 1 (PARP1) inhibitors." (PMID 33662256, 2021). "The ability to detect RAD51 foci in diagnostic FFPE tumor specimens opens the door to its use as a biomarker for HRD in the clinic and in this study, we take two crucial steps towards this goal." (PMID 34203855, 2021). "Here, we show that, using an optimized and calibrated protocol, diagnostic FFPE tumor specimens of EC and OC can be successfully analyzed with the RAD51-FFPE test." (PMID 34203855, 2021). "In this study, we found that the decrease of Rad51 is associated with the increase of its ubiquitination in VPA-mediated radiosensitization for tumor cells in both the in vivo and in vitro working systems." (PMID 33842359, 2021). "Gene expression of FOXM1 and its targets BRCA1/2 and RAD51 were investigated together with tumor susceptibility." (PMID 33668819, 2021). "Other mouse models have also revealed tumor predisposition upon tissue-specific inactivation of the RAD51 loading factors Palb2 and Brca2." (PMID 33923105, 2021). "Overexpressed RAD51 causes increased survival of tumor cells and resistance to DNA-damaging treatments such as radiotherapy and chemotherapy." (PMID 34067336, 2021). "YTR107 caused significant radiosensitization of tumor TICs, consistent with the knowledge that RAD51 can contribute to TIC intrinsic radiation resistance." (PMID 33358698, 2021). "In this context, previous studies have highlighted that increased expression of the major DNA repair protein RAD51 is associated with resistance to chemotherapy in several different tumor types." (PMID 33420377, 2021). "Low RAD51 scores were identified in 11% of all samples, of which one tumor was associated with PARPi response." (PMID 34959671, 2021). "The trial prospectively examined three potential biomarkers of PARP inhibitor activity, a molecular signature of HR deficiency using HRDetect, RAD51 focus formation in a tumor biopsy at the end of treatment, and BRCA1 methylation." (PMID 32471999, 2020). "The advantage of the elevated expression of RAD51 for tumor cells has yet to be sufficiently explained; however, it has been suggested that overexpression of RAD51 is related to tumor progression caused by genomic disruption." (PMID 31534120, 2019). "In this replicative context, combined PARP inhibition with HR deficiency (due to BRCA or RAD51 paralog mutation) results in tumor cell lethality." (PMID 31383866, 2019). "HR was first identified as a tumor suppressor pathway when RAD51 was found to associate with BRCA1 and BRCA2." (PMID 31435521, 2018). "In conclusion, we demonstrated that high cytoplasmic RAD51 expression was associated with MPR (as indicated by the percentage of viable tumor cells) and shorter OS in patients with NSCLC receiving neoadjuvant chemotherapy." (PMID 29673125, 2018). "RAD51 expression level was also significantly associated with MPR as indicated by the percentage of viable tumor cells (P = .01)." (PMID 29673125, 2018). "We demonstrated that cytoplasmic RAD51 expression was associated with both MPR (as indicated by the percentage of viable tumor cells) and OS." (PMID 29673125, 2018). "In this study, we found that cytoplasmic RAD51 expression was associated with MPR (higher percentage of viable tumor cells) and shorter OS time in patients with NSCLC receiving neoadjuvant chemotherapy." (PMID 29673125, 2018). "The role for HSP27 phosphorylation in association with RAD51 in tumor progression is part of ongoing investigations." (PMID 27507046, 2016). "Given the potential linkage of RAD51 with chemo-resistance and genome instability, we proposed that the refractory and aggressive characteristic of the tumor was induced by expression of the RAD51 G151D variant." (PMID 27513445, 2016). "MiRNAs can regulate the activity of RAD51, and miRNA dysregulation has been implicated in neoplasms." (PMID 27733989, 2016).
tumor (continued). "Decreased RAD51AP, encoding an enhancer of RAD51, observed in tumours from ECR patients is consistent with this suggestion, as genetic ablation of RAD51AP1 leads to enhanced sensitivity to chromosome aberrations upon DNA damage." (PMID 26810418, 2016). "In conclusion, the work presented here demonstrates that tumor-associated variants in human RAD51 have functional phenotypes including changes in the physical properties of RAD51–DNA filaments, and changes in the catalytic activities of these filaments." (PMID 25539919, 2015). "Despite extensive studies of human RAD51, there are few reports on the basic biochemical behavior of tumor-associated variants." (PMID 25539919, 2015). "Deficient HR can be deduced from identified inactivating mutations of already known genes (such as BRCA1 or RAD51) in tumor biopsies; however, the major challenge is represented by prediction of the drug resistance development." (PMID 26295265, 2015). "Tumor-associated variants of human RAD51 protein, D149N, R150Q and G151D, are proficient in DNA strand exchange activity but have altered physical and biochemical properties." (PMID 25539919, 2015). "Tumor-associated D149N, R150Q and G151D mutations map to a Schellman loop motif located on the surface of the RecA homology domain of RAD51." (PMID 25539919, 2015). "As in the human tumor cell experiments, only a small fraction of the RAD51 foci seen in Rad54l−/−Rad54b−/− cells were associated with an RPA focus." (PMID 25765654, 2015). "All three of the tumor-associated mutations alter the local surface electrostatic properties of RAD51." (PMID 25539919, 2015). "We determined the ATPase properties of tumor-derived RAD51 variants by performing steady-state kinetics studies with either ATP or ssDNA concentration as the variable." (PMID 25539919, 2015). "To confirm that the enhancement of tumor killing invivo by B02 is caused by targeting RAD51, we investigated the effect of B02 on RAD51 foci formation induced by cisplatin in tumor tissues in mouse xenografts." (PMID 24971740, 2014). "Recently, c-Myc has been reported to transcriptionally activate rad-51 and survivin both of which are firmly linked to radiosensitivity of tumor cells." (PMID 25026294, 2014). "Recent studies have shown that rad-51 and survivin both of which are reported to be firmly linked with radioresistance of tumor cells can be transcriptionally activated by c-Myc." (PMID 25026294, 2014). "After subtraction of spontaneous RAD51 foci formed in the tumor tissues of the untreated mice, B02 caused a 76% decrease in the number of RAD51 foci per nucleus comparing with tumors treated with cisplatin." (PMID 24971740, 2014). "A total of 82 genes previously implicated in processes relevant to tumor progression were screened, of which 25 were selectively induced with overexpression of RAD51 and repressed with knockdown of RAD51." (PMID 24811120, 2014). "Enhanced expression of Rad51 protein in tumour cells is associated with high DNA repair capacity, elevated recombination rates and increased resistance against radio- and chemotherapy." (PMID 15956972, 2005). "Additionally, our data indicate that TP53I11 expression in primary tumours correlates with overall survival, while high RAD51 expression is linked to worse outcomes due to its role in HR and genomic instability." (PMID 41007296, 2025). "Notwithstanding, dominant direct effects persisted in both models, suggesting unmeasured tumor-intrinsic mechanisms (e.g., metabolic reprogramming; homologous recombination competence assessed via RAD51 foci formation) potentially underlie isoform-specific prognostic impacts." (PMID 40849492, 2025). "In addition, it has been well documented that RAD51 overexpression is associated with tumor resistance to chemotherapy." (PMID 37251536, 2023).
tumor (continued). "It was reported that HR deficiency assays, such as detecting nuclear RAD51 foci in tumor cells, could identify patients with BRCA pathogenic variants that are more likely to respond to platinum-containing therapy and PARP inhibitors." (PMID 36865806, 2023). "Therefore, the cells bearing one of these RAD51 mutations would be eliminated, impairing their transformation in tumor cells and in fine tumor development." (PMID 37190078, 2023). "Moreover, dysregulated expression of Rad51 is associated with diverse clinic-pathological factors and prognosis, indicating Rad51 as a potential prognostic marker in many tumor types." (PMID 35875146, 2022). "The tumor was highly proliferative and homologous recombination-deficient by RAD51." (PMID 36185283, 2022). "Importantly, the inhibition of Rad51 showed synthetic lethal effect with the silencing of Sam68, hampering the cell viability of patient-derived BCSphCs and stabilizing the growth of tumor xenografts, including those TNBC carrying BRCA mutation." (PMID 35217791, 2022). "Eleven of the 14 patients with a low RAD51 tumor had a gPALB2 mutation." (PMID 33670893, 2021). "In some isolated cases, mutations of RAD51 have been found in tumours." (PMID 34316706, 2021). "Interestingly, these findings suggest that sufficient endogenous DNA damage for an adequate RAD51-FFPE test is present in the vast majority of diagnostic FFPE tumor blocks." (PMID 34203855, 2021). "In this section describing the mechanisms of PARPi resistance linked to the BRCAm/HRRm status of the tumour, we will highlight whether the discussed mechanism has the potential to restore RAD51 foci formation." (PMID 35008208, 2021). "These two opposing roles of RAD52-dependent SSA make it a potential target of chemotherapy to treat RAD51-deficient tumour, as RAD52 inactivation may specifically inhibit the tumour growth and block additional rearrangements of chromosomes." (PMID 32355220, 2020). "Thus, there is renewed interest in the RAD51 paralogs from a human health concern and the need for isogenic human cell lines to evaluate tumor-derived mutations and support biochemical approaches aimed at understanding their molecular functions." (PMID 31584931, 2019). "Our study presents a novel hyper-recombinant RAD51 tumor-associated variant (RAD51 G151D), providing the first evidence that links altered RAD51 function with therapeutic resistance as well as a novel genetic marker to identify patients at high risk for aggressive and refractory disease." (PMID 27513445, 2016). "Here we show that the G151D tumor-associated RAD51 variant induces a hyper-recombination phenotype." (PMID 27513445, 2016). "Deficiencies in Rad18, FANCD2, BRCA2, and Rad51 are all known to sensitize tumor cells to CPT." (PMID 26871286, 2016). "However, in our cell models, the G151D variant is expressed in the presence of endogenous RAD51 potentially mimicking the heterozygous state present within the patient’s tumor." (PMID 27513445, 2016). "RAD51 overexpression is associated with an increase in DNA repair activity that could account for tumor's resistance to radiotherapy and DNA damaging chemotherapy." (PMID 26910887, 2016). "The results suggest that mutations in RAD51 protein could play important roles in carcinogenesis and tumor progression." (PMID 25539919, 2015). "Increased levels of RAD51 have been observed in tumor cells and were associated with better survival after radiotherapy treatments; thus, RAD51 can be considered as one of the targets to radiosensitize tumor cells." (PMID 26337087, 2015). "Therefore, the motif in which the three tumor-associated mutations occur has rather low freedom of movement, indicating that its position in RAD51 structure is relatively conservative." (PMID 25539919, 2015). "The tumor cells may be susceptible to toxic accumulation of RAD51, if high levels of RAD51 result in an imbalance of RAD51 and RAD54 activity." (PMID 25765654, 2015).